EGFR (epidermal growth factor receptor)
Diseases named in the same sentence as EGFR in open-access papers (continued):
Sharing a sentence is not in itself a finding about the gene and the disease.
lung cancer (continued). "Here, using a syngeneic mouse model of EGFR-mutant lung cancer, we show that tumor regression elicited by osimertinib requires activation of CD8+ T cells." (PMID 36817465, 2023). "EGFR overexpression is an unfavorable prognostic marker in lung cancer, squamous cell carcinoma (SCC), colorectal cancer, and others." (PMID 37190301, 2023). "Such multifunctional nanocarriers with multistage targeting hold promise for improved efficacy of treatment and increased the intracellular availability of anticancer agents for solid tumors with EGFR overexpression, among them lung cancer." (PMID 36865093, 2023). "Several studies have shown that the stability of the EGFR is an important determinant in regulating the progression of lung cancer and that dysregulation of EGFR degradation accelerates tumorigenesis and progression." (PMID 37270563, 2023). "Lung cancer: PAK1 provides resistance to tyrosine kinase inhibitors in both wild-type epidermal growth factor receptor (EGFR) and mutant cells." (PMID 36830998, 2023). "The results indicated that HCPT combined with CRI exerted synergistic effects on the three lung cancer cells through EGFR related pathway." (PMID 36305251, 2023). "The differences between tumor suppressive effects in EGFR-driven lung cancer and the other oncogenic contexts were even more pronounced." (PMID 37828026, 2023). "The LDH level is a known prognostic inflammatory marker in patients with cancer and has been widely studied in patients with lung cancer treated with chemotherapy or patients with EGFR-mutant NSCLC." (PMID 38132403, 2023). "The resulting system is designed to selectively target and treat lung cancer cells expressing EGFR, while also allowing for the imaging and monitoring of the tumor." (PMID 37242668, 2023). "Our study confirmed that Jinfukang has inhibitory effects on the clustering and invasion of lung cancer CTCs, mainly by regulating the EGFR-mediated cytoskeleton regulation pathway to downregulate the expression of JUP protein." (PMID 37723875, 2023). "For instance, epidermal growth factor receptor (EGFR)-tyrosine kinase inhibitors (EGFR-TKIs) are well-studied in the treatment of nonsmall cell lung cancers (NSCLCs)." (PMID 36836537, 2023). "Preliminary results from the phase II WU-KONG trial of sunvozertinib therapy in EGFR ex20ins lung cancer patients have recently been presented, and these demonstrate a high objective response rate of 73.1% in the first-line setting among 26 evaluable patients." (PMID 37622996, 2023). "Targeted therapy was as popular for advanced lung cancer in ACTS as immunotherapy; EGFR inhibitors and anti-angiogenic agents are similarly increasingly used in lung cancer." (PMID 36831362, 2023). "Both EGFR and KRAS are important driver mutations in lung cancer, however, they were mutually exclusive between G1 and G2 groups." (PMID 37388220, 2023). "EGFR-TKI resistance upregulated PD-L1 expression and caused immune escape in lung cancer via activation of phosphatidylinositol-3 kinase (PI3K), mitogen-activated protein kinase (MAPK) and NF-kappa B (NF-κB) pathways." (PMID 36874015, 2023). "Studies on human tissues were initiated due to a potential role of AQP5 in progression of lung cancer and its involvement in EGFR signaling pathways." (PMID 36766810, 2023). "In this prospective study, we analyzed the cancer tissues and cfDNA of patients with lung cancer using NGS simultaneously after EGFR‐TKI resistance." (PMID 38140788, 2023). "Restoration of TUSC2 expression in lung cancer cells significantly inhibits tumor cell growth and colony formation and increases the sensitivity of cultured resistant lung cancer cells to the EGFR inhibitor erlotinib." (PMID 37173921, 2023). "Next, the performance of this method was further evaluated using the lung cancer cell lines and the EGFR L858R mutant statuses were identified using the 10 ng genomic DNA extracted from the NCI-H1975 and A549 cell lines, respectively." (PMID 36985054, 2023).
lung cancer (continued). "This study examined survival by neighborhood‐level socioeconomic and sociodemographic status, and geographical location of advanced lung cancer patients who received gefitinib, an EGFR‐TKI, as first‐line palliative treatment." (PMID 37017510, 2023). "In lung cancer, the potentially APOBEC3-induced C > T EGFR T790 mutation can promote resistance to the EGFR inhibitors gefitinib and erlotinib." (PMID 36978147, 2023). "CXCL10 is a chemokine that is frequently elevated during EGFR-TKI treatment in the tumor microenvironment of lung cancer." (PMID 37484803, 2023). "Dysregulation of EGFR protein stability greatly contributes to aberrant EGFR signaling and lung cancer progression." (PMID 37813845, 2023). "TCM is reported to exert anticancer activity in lung cancer by inducing apoptosis and/or autophagy, inhibiting metastasis, impacting immune reaction, and enhancing the therapeutic effect of EGFR-TKIs." (PMID 36874921, 2023). "CUB domain‐containing protein 1 (CDCP1) contributes to epidermal growth factor receptor (EGFR) tyrosine kinase inhibitor (TKI) resistance in lung cancer treatment." (PMID 37013960, 2023). "A total of 720 patients had baseline tumor samples genetically profiled for 139 key lung cancer-related genes, including EGFR (see the “Methods” section for more details), which enabled the investigation of concurrent genetic alterations." (PMID 36829178, 2023). "Targeted inhibition of the MET/PI3K/AKT signaling pathway enhances the sensitivity of lung cancer cells to EGFR inhibitors." (PMID 38115126, 2023). "This will make major improvement in survivals for stage IB EGFR-mutant lung cancer patients in the near future." (PMID 36925928, 2023). "Three EGFR-activated alterations coupled with NTRK fusions were detected in lung cancer patients, including two non-small cell lung cancer patients and one small cell lung cancer patient." (PMID 37567953, 2023). "To uncover the molecular mechanism of BC‐mediated EGFR‐TKI resistance in lung cancer, we screened and identified nucleolin and hnRNPK that interact with BC." (PMID 36650118, 2023). "Another critical question—which upstream kinases regulate IKKα activation—warrants further investigation because EGFR and KRAS are highly mutated in lung cancer patients." (PMID 36966223, 2023). "In this study, we establish a novel mathematical model of lung cancer evolution under EGFR-targeted therapy based on clinical observations." (PMID 37841421, 2023). "For example, in EGFR‐mutant lung cancer, IGF‐1R signal transduction required for the DT state is regulated via KDM5A demethylation." (PMID 37638338, 2023). "Third-generation epidermal growth factor receptor (EGFR)-tyrosine kinase inhibitors (TKIs) have shown impressive results in EGFR mutant lung cancer (LC) patients in terms of disease control rate with a positive impact on overall survival." (PMID 38213544, 2023). "To elucidate the molecular mechanisms underlying EGFR activation by lorlatinib, we investigated the changes in gene expression between ALK-rearranged lung cancer cells and their DT cells using microarray analysis." (PMID 36702855, 2023). "Preclinical studies have shown a significant increase in VEGFR-1 expression in EGFR TKI-resistant lung cancer cells." (PMID 37951898, 2023). "Increasing evidences about the role of DNA methylation in the molecular pathology of lung cancer highlights the need for robust technologies able to establish if whole methylome, and not only methylation changes in single or few genes, could be associated with EGFR-TKI resistance." (PMID 37152062, 2023).
lung cancer (continued). "A third of the two main types of lung cancers (SC and NSC) involve a mutation in the Egfr gene, which codes for the epidermal growth factor receptor protein (EGFR)." (PMID 37762088, 2023). "We prospectively enrolled patients with lung cancer with first‐line EGFR‐TKI resistance who underwent tissue rebiopsy." (PMID 38140788, 2023). "S2727, also named dacomitinib, is an approved first‐line therapy for metastatic, EGFR‐mutant non–small cell lung cancer (NSCLC)." (PMID 37340596, 2023). "Specifically, a phase Ib/II trial investigating the SHP2i RMC-4630 in combination with an EGFR inhibitor is currently underway in non–small cell lung cancer (ClinicalTrials.gov NCT03989115)." (PMID 36752207, 2023). "The factors related to the enhanced efficacy of immunotherapy in EGFR‐driven lung cancer should be further investigated as it is certain that some patients with EGFR‐mutant lung cancer exhibit a remarkable and durable response to immunotherapy." (PMID 37699785, 2023). "Our findings highlight a new combination strategy to improve the therapeutic response of EGFR mutant-driven lung cancers to osimertinib." (PMID 36817465, 2023). "Dysregulated ncRNA have been shown to play a regulatory role in EGFR‐TKI resistance in lung cancer through modulating multiple signaling pathways, including the PI3K/AKT/mTOR, JAK/STAT, Ras/Raf/MEK/ERK signaling pathways." (PMID 36910653, 2023). "Methylated genes and their functional and biological effects on acquired EGFR-TKI resistance in different lung cancer models." (PMID 37152062, 2023). "Bilateral choroidal metastases from lung cancer symmetrically are rarely seen, and icotinib following by almonertinib was an alternative therapy for choroidal metastasis from NSCLC with EGFR mutation." (PMID 37315930, 2023). "Our results revealed that lung cancer patients who received EGFR-TKIs treatment have an odds ratio of VTE incidence of 4.71 (2.90–7.67, P < 0.01) compared with patients without EGFR-TKI treatment." (PMID 36872336, 2023). "Manoalide, a natural inhibitor of PLA2, has been identified as a potential EGFR-TKI sensitizer for KRAS-mutated and osimertinib-resistant lung cancer organoid by inhibiting the KRAS-ERK signaling pathway." (PMID 37941550, 2023). "Recently, a series of studies linked AXL to several receptor tyrosine kinase inhibitors including EGFR inhibitors in lung cancer, head and neck cancer and colorectal cancer, HER2 inhibitors in breast cancer, and FLT3 inhibitors in AML." (PMID 36835239, 2023). "In each country, there was a consistent relationship between PM2.5 levels (average concentration per geographical area) and estimated EGFR-driven lung cancer incidence." (PMID 37020004, 2023). "Recent lung cancer studies have described relationships between EGFR amplification and an increased incidence of thromboembolic complications." (PMID 37232831, 2023). "Compounds 15 and 18 were then tested in cell proliferation assays on the H1975 lung cancer cell line expressing the double mutant L858R/T790M EGFR." (PMID 36373202, 2023). "Meanwhile, epidermal growth factor receptor (EGFR) has significantly high expression levels on the surface of lung cancer cell-secreted exosomes." (PMID 36834471, 2023). "NF‐κB signaling is reported to promote lung cancer cell survival and residual diseases in the initial stage of EGFR inhibitor treatment." (PMID 37638338, 2023). "In a case report of two patients with lung cancer, hemorrhagic BMs developed 1 month after a combination of EGFR-TKI and radiation therapies." (PMID 36765577, 2023). "The molecular mechanism determining EGFR‐TKI resistance in lung cancer remains incompletely understood." (PMID 37278440, 2023).
lung cancer (continued). "For instance, initial studies with R26-A3B in an EGFR-driven lung cancer model indicate that A3B is capable of fueling tumor evolution and contributing to drug resistance (even in the absence of inflicting overt APOBEC3 signature mutations)." (PMID 37797615, 2023). "One of the mechanisms of developing resistance in lung cancer is through PTEN loss, which contributes to the resistance to EGFR TKIs." (PMID 37190124, 2023). "In vivo, EGFR CAR-T cells also showed activity after infusion into animals bearing human lung cancer xenografts; specifically, they induced tumor regression at 25 days, as evidenced by bioluminescence imaging that showed a reduction in tumor size." (PMID 36873868, 2023). "Tumor cell-derived EVs transport active EGFR molecules to host macrophages in epidermal growth factor receptor (EGFR)-positive lung cancers." (PMID 36832253, 2023). "Collectively, these data indicate that SIRT1 K/D can sensitize KrasMut lung cancer cells to chemotherapy or EGFR TKI treatment." (PMID 37779142, 2023). "Univariate and multivariate logistic regression analyses of various predictive factors for EGFR status in patients diagnosed with non‐small cell lung cancer." (PMID 37425232, 2023). "CRNDE contributes to the resistance to EGFR tyrosine kinase inhibitor in EGFR-mutant lung cancer through eIF4A3/MUC1/EGFR signaling." (PMID 37194105, 2023). "In that respect, activating mutations in the epidermal growth factor receptor (EGFR) represent one of the best known and most commonly found oncogenic drivers in NSCLC, which can be inhibited by targeted therapies." (PMID 35532791, 2023). "Clinical trials with afatinib, pyrotinib, trastuzumab emtansine, and trastuzumab deruxtecan are being evaluated for their efficacy against EGFR‐TKI‐resistant ERBB2 amplified lung cancers." (PMID 38140788, 2023). "The Wnt signaling pathway plays a crucial role in various carcinogenic processes, including colorectal cancer, EGFR mutant lung cancer, lymphoma, and multiple myeloma." (PMID 37047688, 2023). "The EGFR/HER2 inhibitor Gefitinib is a first-generation EGFR TKI approved for lung cancer treatment." (PMID 37601068, 2023). "Stochastic sensors based on maltodextrins with different dextrose equivalent were proposed for the assay of three lung-cancer biomarkers: neuron-specific enolase, carcinoembryonic antigen, and epidermal growth factor receptor." (PMID 37958213, 2023). "Here, we investigated the efficacy of nivolumab maintenance following platinum‐based chemotherapy in patients with EGFR‐mutant non‐small cell lung cancer (NSCLC) with disease progression after EGFR‐TKI." (PMID 37699785, 2023). "EGFR is a driver of tumorigenesis and is identified as a biomarker of resistance in tumors, especially in glioblastoma, breast, and lung cancer." (PMID 37671046, 2023). "Compared with first‐ and second‐generation TKIs, osimertinib is a third‐generation EGFR‐positive lung cancer targeted medication that significantly improves patients’ overall survival and progression‐free survival." (PMID 38077251, 2023). "Despite the success of EGFR-TKIs therapy in the treatment of lung cancer, the acquired resistance limits the ability to translate this method into a curative treatment." (PMID 37730961, 2023). "Another study showed GM3 to induce sensitivity of EGFR-TK blocker type chemotherapeutic drugs in 3LL lung cancer cell lines by increasing EGFR protein levels." (PMID 38089042, 2023). "Deciphering the when and how to use immunotherapeutic agents in EGFR-positive NSCLC is a current challenge in clinical lung cancer research." (PMID 36765799, 2023). "Lung cancer has seen in the last years a revolution in treatment strategy with the use of several classes of EGFR inhibitors." (PMID 37476385, 2023).
lung cancer (continued). "In lung cancer, we and other groups reported that activation of HGF/MET causes resistance to EGFR‐TKIs and ALK‐TKIs in EGFR‐mutated NSCLC and ALK‐rearranged NSCLC, respectively." (PMID 36416133, 2023). "CAFs have a critical role in the resistance of lung cancer to epidermal growth factor receptor (EGFR) TKIs through the induction of EMT via CAF-mediated signaling pathways." (PMID 36672284, 2023). "In line with the findings in breast cancers, EGFR expression is correlated with the highly expressed PELI1 in these two lung cancer cell lines." (PMID 36841821, 2023). "The standard of care for patients with advanced epidermal growth factor receptor (EGFR) mutation-positive, nonsmall cell lung cancer is EGFR tyrosine kinase inhibitors (EGFR-TKIs)." (PMID 37179737, 2023). "Mechanistically, JAC4 reduced the PI3K/AKT overactivation caused by both EGFR overexpression and mutations in NSCLC; JAC4 rescued JWA transcription in lung-cancer cells by binding to CTBP1." (PMID 37240137, 2023). "These include the fact that a potential subtype of sensitive tumors (EGFR mutant lung cancer or HER2-amplified breast cancer) to target in such a blind primary prevention trial is unclear." (PMID 37169023, 2023). "Our data showed that AICAR caused less cytotoxicity in these stromal cells (EC50: 1.20 ± 0.13 mM) than in EGFR-mutant lung cancer cell lines (p < 0.01)." (PMID 36810913, 2023). "Aberrant activation of the epidermal growth factor receptor (EGFR/ERBB1) contributes to lung cancer." (PMID 36869126, 2023). "Among lung cancers, NSCLC accounts for a larger proportion, with a higher incidence of LUAD, accompanied by the most common EGFR mutation." (PMID 37576883, 2023). "Their findings revealed that a small subset of PC9 non‐small cell lung cancer (NSCLC) cells survived from erlotinib (an EGFR inhibitor) treatment at a lethal dose." (PMID 37638338, 2023). "We believe that CD73 inhbition as a therapeutic target can be applied to other lung cancer types outside of the current scope of EGFR mutant LUAD and unresectable NSCLC." (PMID 37033953, 2023). "Subsequently, testing combinations of EGFR and FGFR inhibitors revealed that the combination was able to overcome EMT-dependent resistance to EGFR-specific TKIs in models of EGFR-mutated lung cancer." (PMID 37894376, 2023). "Meanwhile, in the nude mouse model, EGFR‐TKI combined with anlotinib significantly inhibited the proliferation of lung cancer cells." (PMID 36843208, 2023). "Here we describe the effects of 8PN on lung cancer cells, most notably its synergism with EGFR TKIs in TKI‐resistant cells." (PMID 37013960, 2023). "Overall, through multiple screening analyses using various databases, we were able to pinpoint LAMC2 as a key gene necessary for both EGFR TKI sensitivity as well as the development of lung cancer." (PMID 37542131, 2023). "Together, our findings will give novel insights into the role of CNOT3 in lung cancer malignancy and provide a promising strategy to resolve both EGFR-TKIs resistance and tumor progression." (PMID 37919290, 2023). "In the lung cancer model, MM-121 showed an additive effect to reduce tumor growth when combined with the anti-EGFR antibody cetuximab." (PMID 37947595, 2023). "Our results indicated that the combination of HCPT and CRI inhibited the different lung cancer cells growth and induced the cell apoptosis through regulating the EGFR-related downstream signalling pathways, which was similar to the previously reported." (PMID 36305251, 2023). "In this study, the combination of JAC4 and osimertinib synergistically inhibited the tumor-bearing growth and metastasis of EGFR-mutant lung-cancer cells in model mice." (PMID 37240137, 2023). "An elegant study demonstrated that anti-estrogen fulvestrant and pan-HER inhibitor (dacomitinib) reduced the oncogenic interplay between ER and RTKs (EGFR) to exert synergistic anti-tumor effects in mouse models of KRAS mutant lung cancer." (PMID 37686465, 2023).